HNRNPA3P6 (heterogeneous nuclear ribonucleoprotein A3 pseudogene 6)
Gene: Processed pseudogene on chromosome 3 (75,214,631 to 75,215,636, forward strand). Ensembl gene ENSG00000213300.
Diseases named in the same sentence as HNRNPA3P6 in open-access papers:
HNRNPA3P6 is named in the same sentence as 1 disease in open-access papers, as found by Europe PMC text mining. Sharing a sentence is not in itself a finding about the gene and the disease.
HNRNPA3P6 shares sentences with these, for which no sentence is quoted: HIV-1 infection (1 paper).